NOTCH1 (notch receptor 1)
Diseases named in the same sentence as NOTCH1 in open-access papers (continued):
Sharing a sentence is not in itself a finding about the gene and the disease.
colorectal cancer (continued). "Several investigations indicate that overexpression of Notch1, Jag1, and Jag2 was found in human intestinal adenomas, implying that elevated Notch signaling might be responsible for colorectal cancer initiation." (PMID 32211044, 2020). "Additionally, miR-139-5p successfully arrested growth and infiltration of colorectal cancer cells by inhibiting NOTCH1." (PMID 32507766, 2020). "Also, Notch1 and Notch2 have been correlated with opposite clinical outcomes in colorectal cancer (CRC)." (PMID 32630477, 2020). "Moreover, downregulating lncRNA RP11-59H7.3 resulted in a reduction in levels of NOTCH1, and this led to growth suppression for colorectal cancer cells." (PMID 32507766, 2020). "Notch-1 and Notch-2 function in opposite ways in colorectal cancer." (PMID 31198409, 2019). "High expression of the ligand JAG1, which is regulated by β-catenin, may upregulate the expression of Notch-1 in colorectal cancer, which persists throughout the process of tumor growth." (PMID 31198409, 2019). "To further validate the clinical value of our study, we then examined if Notch1 expression could assist in identifying CSCs in chemically induced colon tumours, the most predominant location in colorectal cancer (CRC) patients." (PMID 30696875, 2019). "Similarly, Notch1 and Notch2 have been reported to have opposite prognostic effects in patients with colorectal cancer." (PMID 29963552, 2018). "Recently, Zhang et al43 demonstrated that the Notch1 signal transduction pathway mediates the effect of COX-2 selective inhibitors on colorectal cancer cells, and also discovered the mechanism of the Notch1 pathway which regulates the proliferation and apoptosis of colorectal cancer cells." (PMID 30013305, 2018). "A recent study showed that miR‐139‐5p could control cell growth, cell cycle, and apoptosis by targeting NOTCH1 in colorectal cancer (CRC)." (PMID 29719937, 2018). "The expressions of NOTCH1 and miR-21 were positively correlated with colorectal cancer development." (PMID 28793339, 2017). "Deregulated expression of Notch1 and Jagged1 is observed in colorectal cancer." (PMID 26650241, 2015). "Our results suggest that NOTCH1 might serve as a prognostic marker for colorectal cancer in the metastatic setting." (PMID 26394830, 2015). "High expression of Notch1 was found in 268 of 462 (58.0%) colorectal cancer tissues." (PMID 24312514, 2013). "Our observations showed that Notch1 might become a valuable predictor for prognosis and survival among colorectal cancer patients." (PMID 24312514, 2013). "We analyzed the associations between levels of Notch1 expression and a series of clinicopathological characteristic, including age, sex, LNM, infiltrate depth, differentiation, tumor location, TNM pathologic stage, in colorectal cancer patients." (PMID 24312514, 2013). "The protein expression of Notch1 was examined by immunohistochemistry in 901 clinical specimens with colorectal diseases, including 220 patients with ulcerative colitis, 232 patients with colorectal adenoma and 449 patients with colorectal cancer." (PMID 24312514, 2013). "We then observed that Notch1 was overexpressed in colorectal cancer tissues." (PMID 24312514, 2013). "Moreover, the expression of NOTCH1, -3 and -4 receptors was reported to be significantly higher in colorectal cancers compared to normal and adenoma tissues, and patients overexpressing NOTCH3 and NOTCH4 receptors, and the HEY1 transcriptional target, exhibit poorer overall survival." (PMID 37860822, 2023). "In order to evaluate whether gender played any role in the association of NOTCH1-rs3124591, NOTCH2-rs11249433, NOTCH3-rs1043994, and NOTCH4-rs3830041 with colorectal cancers, the study subjects were grouped as males and females for counting the genotype and allele frequencies." (PMID 34257585, 2021).
colorectal cancer (continued). "Early onset colorectal cancer patients from our study showed more frequently mutated NOTCH1 tumor suppressor and the DNA strand break repair gene PALB2, and mutations of these genes can be related to the early tumor initiation and generally worse prognosis from young colorectal cancer patients." (PMID 35003350, 2021). "Finally, our findings reveal that interfering with the lncRNA RP11-59H7.3/miR-139-5p/NOTCH1 signals could assist researchers in finding novel options for suppressing progression of colorectal cancer." (PMID 32507766, 2020). "Moreover, miR-139-5p can sensitize colorectal cancer cells to 5-fluororacil by targeting NOTCH-1." (PMID 30170559, 2018). "Besides, miR‐139‐5p is able to repress the activation of AMFR and NOTCH1 in colorectal cancer." (PMID 28780773, 2017). "Cellular experiments have confirmed that vitamin D can inhibit the proliferation, migration, and invasion of colorectal cancer cells (SW480) and promote their apoptosis by downregulating the Notch1 pathway." (PMID 41602823, 2026). "In colorectal cancer (CRC), circAPLP2 sponged miR-101-3p, activating Notch1 and promoting tumor progression, while circAPLP2 knockdown inhibited tumor growth and metastasis." (PMID 40074445, 2025). "In colorectal cancer, silencing STRAP can form inhibitory chromatin domains to suppress the activation of the Notch1-Hes1 axis, weaken CSC self-renewal, and enhance chemosensitivity." (PMID 40755759, 2025). "However, NOTCH1 mutation (HR 4.18, 95% CI 1.65–10.61, P = 0.003), Lysine (K)‐specific methyltransferase (KMT) 2C mutation (HR 2.91, 95% CI 1.09–7.82, P = 0.034) and deleted in colorectal cancer (DCC) mutation (HR 3.72, 95% CI 1.11–12.50, P = 0.034) were associated with shorter OS." (PMID 37864465, 2024). "Up-regulation of ZNF671 in colorectal carcinoma (CRC) cells resulted in suppressive effects on proliferative ability and metastatic potency via the deactivation of Notch signaling, with decreases in expression of Notch1, NICD, HES1 and HEY1." (PMID 39595048, 2024). "Some studies have also shown that hPER3 negatively regulates Notch1 signaling pathway, e.g., enhancement of hPER3 has markedly inhibited Notch1 and JAG1 expression in human colorectal cancer stem-like cells and prostate cancer cells." (PMID 33741899, 2021). "In hepatocellular and colorectal carcinomas, FBXW7 under‐regulation affects c‐Myc and NOTCH1 expression levels, which can be directly correlated to cell proliferation, migration, invasion, and hence poor prognosis." (PMID 33822486, 2021). "Mechanistically, FAM83D suppression promoted colorectal cancer cell apoptosis, inhibited cell proliferation, cell migration, and invasion through inhibiting the FBXW7/Notch1 signal pathway." (PMID 33363204, 2020). "In colorectal cancer, FAM83D knockdown up-regulated the protein expression level of FBXW7, but diminished the Notch1 protein expression level." (PMID 30910840, 2019). "Transcriptional repressor Kruppel-like factor (KLF4) inhibits the abnormally differentiated cells in colorectal cancer and HES-1, a downstream molecule of Notch-1, can inhibit the expression of KLF4." (PMID 31198409, 2019). "We and others have described activation of NF-κB via the IKK signalosome by Notch1 in T-ALL, cervical cancer and colorectal cancer." (PMID 30564555, 2018). "Epithelial to mesenchymal transition (EMT) in colorectal cancer (CRC) has been attributed to activation of AKT and Notch1 signaling pathways." (PMID 30038258, 2018). "MiR-139-5p promotes cell cycle arrest in G0/G1 phase by targeting NOTCH1 in colorectal cancer, and miR-378a-5p inhibits cell growth and the G1/S transition by targeting CDC40 in colorectal cancer." (PMID 26462034, 2015). "MiR-139 reportedly target Rho-kinase 2 in hepatocellular carcinoma 11, NR5A2 in esophageal cancer 14, NOTCH1 and IGF1R in colorectal cancer 15,28." (PMID 26256448, 2015).
colorectal cancer (continued). "Blocking the Notch1/Hes1 axis enhances radiosensitivity by suppressing proliferation, exacerbating radiation-induced DNA damage (e.g., DSBs), and impairing DSB repair in colorectal cancer." (PMID 40755759, 2025). "Notch-1 has previously been targeted for colorectal cancer treatment but not in relation to β-1,4-GalT-V." (PMID 40869407, 2025). "Despite this apparent antagonistic functions in primary colorectal cancer, in non-pathological intestinal epithelium, NOTCH1 and NOTCH2 receptors were shown to operate in a redundant manner for the maintenance of pluripotent progenitors in endothelial crypts." (PMID 37860822, 2023). "The aberrations found in this study (losses of TSC2, COL1A1, NOTCH1, MIR4673 and GNAS, and gains of MALAT1 and TALAM1) may serve as candidate biomarkers for early detection of colorectal cancer onset." (PMID 35887000, 2022). "For example, miR-139 can suppress endometrial cancer cell growth and migration via down-regulation of HOXA10, restore docetaxel-chemosensitivity by targeting Notch1, decrease tumor cell over-proliferation and EMT process in metastatic prostate and colorectal cancer cells." (PMID 34070538, 2021). "In this case-control study, TaqMan genotypic analysis of rs3124591 in NOTCH1 and rs3820041 in NOTCH4 did not exhibit association with breast as well as colorectal cancers." (PMID 34257585, 2021). "Furthermore, rAF-IL12 also exhibited its apoptotic activity as it significantly (p < 0.05) reduced the expression of NOTCH-1 in vivo; NOTCH-1 signaling pathway is involved in pathogenesis of colorectal cancer." (PMID 32612457, 2020). "In non-Aes mutant colorectal cancer, ABL1 can also increase NOTCH1 and MYC protein levels leading to enhanced tumor growth." (PMID 34022881, 2021). "Moreover, a negative correlation between Notch1 target gene Notch-regulated ankyrin repeat protein 1 (NRARP) and WNT target genes was found in human colorectal cancer." (PMID 33968932, 2021). "Besides, it has been shown that the Bone Morphogenetic Protein (BMP) non-canonical activation of NOTCH1 pathway was participating in epithelial-to-mesenchymal transition (EMT) and led to poorer prognosis in mesenchymal-subtype of colorectal cancer, a subtype featuring EMT and MSI high signatures." (PMID 37860822, 2023).
melanoma (110 papers, 2009 to 2026). A malignant, usually aggressive tumor composed of atypical, neoplastic melanocytes. "In melanoma, NOTCH1 expression was shown to cause an immunosuppressive tumor microenvironment while its inhibition enhanced immunotherapy efficacy." (PMID 39451738, 2024). "Our data show that loss of Notch 1 or Notch2 cannot substitute for the tumor suppressor functions of Pten in BRAFV600E-induced melanoma." (PMID 36672468, 2023). "Our data show that NOTCH1 expression tends to be associated with less aggressive melanoma and better survival." (PMID 36672468, 2023). "In this aspect, loss of active NOTCH1 signaling in mesenchymal stem cell derived fibroblasts (MSC-DFs) have been implicated to induce CD271+/Nestin+ melanoma initiating cells along with enhanced spheroid formation ability." (PMID 38269089, 2023). "Notch1 deficiency sensitizes melanoma cells to stress-induced cell death and repress proliferation ability in part by inhibiting CCND1, resulting in decreasing in melanoma growth." (PMID 35585935, 2022). "A recent study utilized an exome sequencing screen to characterize the functional impact of FBXW7 mutations in melanoma, and highlight its substrate NOTCH1 as a suitable therapeutic marker in the clinical setting." (PMID 33822486, 2021). "FBXW7 as a critical tumor suppressor that is reportedly mutated and inactivated in melanoma, resulting in constitutive NOTCH1 activation." (PMID 33822486, 2021). "Mutations characterized previously in CLL, ATL and melanoma by dysregulated NOTCH1, a substrate of FBW7, were tested for LT and sT binding." (PMID 32427880, 2020). "In healthy skin, Notch drives epidermal differentiation while a loss of Notch1 correlates with non-melanoma appearance, such as increased susceptibility of basal cell carcinoma (BCC)." (PMID 32796631, 2020). "A recent study provided evidence of the recurrent mutations of the FBXW7 gene in human melanomas; in this context, it is important to point out that NOTCH1 is a substrate of this gene." (PMID 29156643, 2017). "Of significance are the melanoma-related genes NOTCH1, NOTCH2, WNT3a, and WNT5a, each of which are associated with two or more UV-miRNAs that can directly target these respective genes." (PMID 27149382, 2016). "With respect to effects of different types of tumor stromal fibroblasts on melanoma growth, we observed that the loss of Notch1 in host stromal fibroblasts had little effect on B16 melanoma cell skin growth in LOFNotch1 mice." (PMID 27813493, 2016). "al. found that FOXP3 upregulation mediated by Notch1 signaling could potentially serve as a marker for tumor aggressiveness and metastasis, and that NOTCH1 inhibition causes the significant reduction of melanoma cell proliferation and viability." (PMID 36672468, 2023). "e., the loss of Notch1 or Notch 2 or both fail to induce melanoma in BRAFCA mice." (PMID 36672468, 2023). "Consistently, a Notch1 decoy that inhibits the interaction Notch–Dll caused a hypersprouting phenotype, stimulated dysfunctional tumor angiogenesis, and hampered tumor growth in xenograft mouse models of mammary, pancreatic, lung tumors, and melanoma." (PMID 30154786, 2018). "Moreover, in keeping with the tumor suppressor role of NOTCH1 in skin, it is of note that melanoma cancer cell lines contained the fewest NOTCH1 mutations and melanoma was also the only cell type that had a higher mutation frequency in primary tumors compared to cell lines." (PMID 25907971, 2015). "Here we show that Notch1 is expressed in melanoma brain metastasis and that, given its role in all hallmarks of melanoma, can be a new therapeutic target for MBMs." (PMID 40437523, 2025). "DLL4 was identified as ligand of Notch1 in hepatocellular carcinoma, Notch4 in glioblastoma and Notch3 in melanoma." (PMID 39951484, 2025). "Activation of Notch1 enhances N-cadherin expression, thereby facilitating melanoma cell adhesion through N-cadherin interaction." (PMID 40399946, 2025).
melanoma (continued). "Co-inhibition of Notch1, via anti-N1, and ChK1, via prexasertib (prex), exacerbated DNA damage increasing melanoma cell death." (PMID 40437523, 2025). "The extreme stress melanoma cells experience while undergoing blockade of Notch1 and ChK1, is likely to lead to cell death." (PMID 40437523, 2025). "To investigate further the mechanisms of Notch1 in melanoma, we performed RNAseq on K457 melanoma cells treated with IgG control or anti-N1 for 48 h." (PMID 40437523, 2025). "Though the response varies among cell lines, possibly due to the level of Notch1 expression and therefore dependency on the signaling pathway, these data indicate inhibiting Notch1 promotes melanoma cell death." (PMID 39491031, 2024). "A complete heat map depicting all TCGA tumors and representative correlation analyses of Notch1 and immune infiltrates in melanoma is shown in Suppl." (PMID 39491031, 2024). "Here, we addressed the therapeutic effects of a novel anti-Notch1 neutralizing antibody we produced, alone and in combination with immune checkpoint inhibition in melanoma models." (PMID 39491031, 2024). "Previous studies have shown that Notch1 is highly expressed in 50-60% of melanomas and 65% of melanoma cell lines, while it is very low or undetectable in normal melanocytes and pigmented nevi." (PMID 39611156, 2024). "The heat map, showing only melanoma samples (total, metastatic and primary), shows that Notch1 inversely correlates with CD8+ T cells, while it positively correlates with Tregs and MDSCs." (PMID 39491031, 2024). "In conclusion, we propose selective Notch1 inhibition with our anti-N1 antibody as a novel, effective anti-melanoma therapy, particularly in combination with immunotherapy." (PMID 39491031, 2024). "Considering the oncogenic role of Notch1 signaling in melanoma, a phase II trial using broad Notch signaling inhibitors surprisingly only showed minimal clinical activity against metastatic melanoma." (PMID 38705997, 2024). "Notch1 was also recently shown to mediate the proangiogenic activity of ALDH1A1-overexpressing melanoma cells." (PMID 39199632, 2024). "We propose elevated Notch1 signaling activity is also a mechanism of resistance to melanoma immunotherapy." (PMID 39491031, 2024). "In melanoma cell lines from both mice and humans, Notch1 also induced CD133 expression by the binding of activated Notch1 to the Prom1/PROM1 promoter." (PMID 38532366, 2024). "To assess Notch1 and Notch2 activity, we used SNAP23 and BCAT2, two downstream targets of Notch1 and 2, respectively, that we identified by a microarray analysis of human melanoma cells in which each Notch receptor was inhibited by a specific shRNA." (PMID 39491031, 2024). "Overall, these data demonstrate that selective inhibition of Notch1 exerts anti-melanoma therapy with immunomodulatory activity that boosts ICI treatment with anti-PD-1." (PMID 39491031, 2024). "These Notch1−/−CAF-induced CD271+ melanoma initiating cells also exhibited increased stem-markers sox2, oct4 and nanog; proliferative capacity, invasiveness, and enhanced lung metastasis in vivo." (PMID 38269089, 2023). "The chemical and genetic inhibition of Notch1 suppressed tumor growth in a xenograft melanoma model." (PMID 36901857, 2023). "In macrophages, in vitro models of melanoma show a higher correlation of NOTCH1, NOTCH2, and Hes1 expression in M1 macrophages." (PMID 37893184, 2023).